MGMT (O-6-methylguanine-DNA methyltransferase)
Diseases named in the same sentence as MGMT in open-access papers (continued):
Sharing a sentence is not in itself a finding about the gene and the disease.
glioblastoma (continued). "Also molecular markers known to influence glioblastoma prognosis—such as IDH mutation status, MGMT promoter methylation, and ATRX expression—were not assessed, which restricts comprehensive molecular stratification." (PMID 41577996, 2026). "Non-methylated MGMT glioblastoma patients seem to benefit more from gross total resection." (PMID 41247617, 2025). "A phase III CENTRIC trial and a phase II CORE trial both in completed state and investigated that Cilengitide failed to improve progression-free survival (PFS) and overall survival (OS) for glioblastoma patients without MGMT methylation, which precludes its clinical utilization." (PMID 40352270, 2025). "This is important to note because epigenetic silencing of the MGMT promoter via methylation impairs the repair of DNA damage caused by temozolomide, thereby conferring improved survival outcomes in patients with glioblastoma compared to those patients without MGMT promoter methylation." (PMID 39997634, 2025). "This reduction in MGMT transcription levels, prompted by LB-100, could be advantageous for glioblastoma patients, as the absence of MGMT expression is regarded as a favorable prognostic indicator for temozolomide-treated glioblastoma patients." (PMID 40006556, 2025). "In glioma, it is well known that O-6-methylguanine-DNA methyltransferase (MGMT) promoter methylation status is both prognostic and predictive of treatment outcome with temozolomide, so treatment decisions in clinical routine for glioblastoma are mainly based on it." (PMID 40075591, 2025). "Notably, in this study, patients with MGMT-methylated recurrent glioblastoma had a PFS twice as high as those without methylation." (PMID 40963873, 2025). "By contrast, large, randomized studies of PD-1 monotherapy have been negative: nivolumab did not improve overall survival versus bevacizumab in recurrent disease and nivolumab with radiotherapy did not surpass temozolomide-radiotherapy in newly diagnosed, MGMT-unmethylated glioblastoma." (PMID 41583467, 2025). "Histopathological and molecular analysis confirmed glioblastoma multiforme (GBM), IDH-wild type, with MGMT promoter methylation." (PMID 41458749, 2025). "However, emerging evidence suggests that the predictive value of MGMT methylation in glioblastoma is not uniform but is modulated by broader epigenetic subgroups and degrees of methylation." (PMID 41346390, 2025). "Interestingly, a recent study identified that a subgroup of glioblastoma patients with high TIM-3 protein expression together with MGMT promoter non-methylation correlated strongly with shorter survival time." (PMID 40072074, 2025). "The high proportion of MGMT-methylated tumors (75%) in the entire cohort may reflect selection bias toward surgically accessible cases, despite the subgroup analysis of 16 IDH-wild-type glioblastomas." (PMID 41247617, 2025). "Moreover, plasma LDHA, CCL2, and CCL7 levels were not related to the status of recurrence, gender, age, and MGMT methylation in glioblastoma patients." (PMID 38443336, 2024). "A phase III clinical trial ascertained that patients with de novo O-6-methylguanine-DNA methyltransferase (MGMT) unmethylated glioblastoma that received nivolumab plus radiotherapy did not benefit from nivolumab (CheckMate-498) when compared to standard chemoradiotherapy." (PMID 38672638, 2024). "In grade 4 glioblastoma multiforme (GBM), wild-type isocitrate dehydrogenase (IDH) status showed the best treatment outcomes with temozolomide (TMZ) in patients with O-6-methylguanine-DNA methyltransferase (MGMT) promoter methylation." (PMID 39439623, 2024). "GBM, glioblastoma; IDH, Isocitrate Dehydrogenase; EGFR, epidermal growth factor receptor; MGMT, O6-methylguanine-DNA methyltransferase; ATRX, Alpha thalassemia/mental retardation syndrome X-linked; PFS, progression-free survival; OS, overall survival." (PMID 39371551, 2024).
glioblastoma (continued). "In addition to predicting patient response to chemotherapy, MGMT methylation can also be used to predict radiotherapy response and prognosis for glioblastoma without adjuvant alkylating chemotherapy." (PMID 38681199, 2024). "However, there is lack of level 1 evidence for impact of MGMT methylation for inoperable glioblastoma undergoing biopsy and systemic treatment." (PMID 39367282, 2024). "Radiological scans have proved an effective non-invasive technique for early-stage MGMT prediction in patients suffering from GBM with screening and diagnosis, support for treatment regimens, prognosis evaluation, and follow-up for advanced-stage of glioblastoma." (PMID 38291266, 2024). "Surprisingly, in the same CRISPR-based screens that revealed the critical role of the FA genes in TMZ/MNNG resistance, PARP1 depletion did not hyper-sensitize MGMT-negative glioblastomas to TMZ and led to only a minor increase in MNNG sensitivity in RPE1 cells." (PMID 39011394, 2024). "For example, tumor-induced edema could be used to predict the survival outcomes of glioblastoma patients based on MGMT promoter methylation, not the IDH-1 status." (PMID 37754483, 2023). "A phase III clinical trial comparing nivolumab plus radiotherapy with standard chemoradiotherapy further confirmed that patients with de novo O-6-methylguanine-DNA methyltransferase (MGMT) unmethylated glioblastoma did not benefit from nivolumab therapy (CheckMate-498)." (PMID 36229714, 2023). "As MGMT promoter methylation status is not only prognostic in wild-type GBMs,35,36 but also predictive of glioblastoma response to treatment with temozolomide, our lack of controlling it as confounding factor may have affected our results." (PMID 38026584, 2023). "Temozolomide (TMZ) is an important first-line treatment for glioblastoma (GBM), but there are limitations to TMZ response in terms of durability and dependence on the promoter methylation status of the DNA repair gene O6-methylguanine DNA methyltransferase (MGMT)." (PMID 37894860, 2023). "Overall, we conclude that the modified RANO criteria might not be entirely suitable for patients with MGMT-methylated glioblastoma receiving CCNU/TMZ treatment." (PMID 37728779, 2023). "MGMT-methylated tumors: A European Organisation for Research and Treatment of Cancer (EORTC)/National Cancer Institute of Canada (NCIC) open-label trial was the first to show that concurrent and adjuvant treatment with temozolomide was effective in adults with glioblastoma." (PMID 37881322, 2023). "We conclude that obesity might be a prognostic marker in newly diagnosed MGMT-methylated but not MGMT-unmethylated glioblastoma." (PMID 35704157, 2022). "Glioblastoma with MGMT negative results had a better prognosis." (PMID 36483042, 2022). "Standard therapy for recurrent MGMT-methylated glioblastoma is not standardized and may consist of re-resection, re-irradiation, and chemotherapy with temozolomide (TMZ), lomustine (CCNU), or a combination thereof." (PMID 35045869, 2022). "For example, the National Center for Tumor Diseases-Heidelberg Neuro Master Match (N2M2) (NCT03158389) is a trial currently ongoing where molecularly matched targeted therapies plus RT in patients with newly-diagnosed glioblastoma without MGMT promoter are being evaluated." (PMID 35327445, 2022). "Phase I of the CheckMate 143 trial (NCT02017717), which was the first to evaluate immune checkpoint inhibition with the first-line treatment of glioblastoma, showed that patients with unmethylated MGMT had similar overall survival with or without TMZ combined with nivolumab plus radiotherapy." (PMID 36466873, 2022).
glioblastoma (continued). "Interestingly, under the same conditions applied to treat U-87 MG cells, Cyn inhibited the cell viability of patient-derived glioblastoma cell lines NULU and ZAR, known to be characterized by the wild-type IDH status and by an unmethylated MGMT gene promoter and, thus, by a TMZ-resistant phenotype." (PMID 35884887, 2022). "Moreover, we have not been able to demonstrate any MGMT induction by IR in glioblastoma cells in vitro." (PMID 35785203, 2022). "TMZ, which is the current standard of care for glioblastoma multiforme (GBM) together with radiotherapy after resection, might sensitize tumor cells to γδ T-cell recognition through upregulation of NKG2D ligands but it also causes lymphocytopenia that is avoided by MGMT expression." (PMID 35784326, 2022). "Furthermore, our data confirm MGMT promoter methylation as a powerful predictor of outcome in both elderly and non-elderly glioblastoma patients." (PMID 32748120, 2021). "However, MGMT is able to selectively remove these adducts; thus, cancers expressing little or no MGMT, such as MGMT negative glioblastomas, remain sensitive to treatment." (PMID 34830134, 2021). "In both TCGA and CGGA dataset, the results showed that the expression level of AEBP1 was increased in glioblastoma (GBM) samples, IDH wild-type samples, and MGMT promoter unmethylated samples." (PMID 34373835, 2021). "Inactivation through promoter methylation of the O6-methylguanine-DNA methyltransferase (MGMT) gene, which impairs the ability to repair DNA damaged induced by alkylating agents such as TMZ, has been described as a relevant biomarker for clinical decision-making in glioblastoma treatment." (PMID 33001310, 2021). "Therefore we examined whether oxelaidin is effective in inhibiting chemoresistance of glioblastoma cell lines, including constitutively active EGFR vIII-expressing U87MG (U87MG-vIII), temozolomide-resistant U87MG (U87MG-TMZR) and high MGMT-expressing T98G." (PMID 33980886, 2021). "Indeed, tumor progression-free survival of glioblastoma patients with MGMT methylation is better than that of patients with non-methylated glioblastoma." (PMID 33661424, 2021). "These previous studies on Ki-67 did not include MGMT promoter methylation status and post-surgical treatment in the survival analysis although these parameters have significant prognostic impact on the outcome in the glioblastoma patients." (PMID 34504133, 2021). "Regarding these results, we hypothesize that the MGMT-negative glioblastoma cell line U87 might serve as a model for highly aggressive, mHsp70-positive primary glioblastomas without IDH-1 mutation." (PMID 32276468, 2020). "Therefore, patients with MGMT methylated glioblastoma are more sensitive to neo-adjuvant temozolomide than those without MGMT methylated glioblastoma." (PMID 32477929, 2020). "Therefore, we have initiated this study to re-evaluate the topographical distribution of glioblastoma with and vs. without MGMT promoter methylation in the largest homogenous IDH wildtype glioblastoma population to date." (PMID 32477929, 2020). "The methylation status of the O6-methylguanine-DNA methyltransferase (MGMT) promoter is used routinely to guide chemotherapeutic treatment decisions, especially in glioblastoma (GBM) (e.g., grade IV astrocytoma), which is the most common type of DG." (PMID 32563269, 2020).
glioblastoma (continued). "Thus, neither the unmethylated MGMT promoter of TMZ-resistant LN18 glioblastoma cells was converted into a methylated promoter, nor the methylated promoter of TMZ-sensitive LN229 cells was converted into an unmethylated one." (PMID 32977591, 2020). "The authors found that maximal resection of CE and NCE tumor was associated with longer overall survival in younger patients with IDH wildtype glioblastoma regardless of MGMT methylation status (subset of 190 patients with known IDH mutation and MGMT methylation status)." (PMID 32766140, 2020). "Interestingly, DSF did not mediate radio-sensitization in glioblastoma cells with a methylated MGMT promoter." (PMID 33260923, 2020). "Lastly, the addition of nivolumab to the first-line treatment with temozolomide and radiotherapy in newly diagnosed MGMT-methylated glioblastoma patients (CheckMate-548; NCT02667587), failed to meet one of its primary endpoints, i.e., PFS, and is currently awaiting the overall survival data." (PMID 32143288, 2020). "Thus, the two cell types used in this study represented TMZ-resistant glioblastoma regardless of MGMT status." (PMID 31658771, 2019). "Among them, T98G is overexpressed O6-methylguanine-DNA methyltransferase (MGMT), which is widely accepted mechanism to resist temozolomide (TMZ), but eventually PF still showed strongly suppression in T98G, which suggests that PF can exert wide suppression function in glioblastoma." (PMID 29423667, 2018). "In patients with a methylated MGMT gene promoter, the mOS of 34.7 months from surgery also compares favorably with SOC in past studies as well as with the mOS reported for the control arm SOC treatments in other recent glioblastoma trials in similar patient populations." (PMID 29843811, 2018). "50% of glioblastomas patients with low level of MGMT could not benefit from TMZ therapy, which suggested that the additional factors participated in TMZ resistance." (PMID 29487691, 2018). "Accordingly, TTFields may be particularly attractive for the majority of glioblastoma patients with tumors that are unlikely to benefit from TMZ treatment because of the unmethylated MGMT promoter." (PMID 28425987, 2017). "However, promoter methylation and genotypes collectively are not correlated with OST on glioblastoma patients with a hypo-methylated MGMT promoter." (PMID 28575062, 2017). "All these microRNA-MGMT interactions thus deserve further investigation using 3′UTR luciferase assays, co-immunoprecipitation with biotinylated miRNAs and reversal of effect by anti-mirs, in parallel glioblastoma cell lines expressing at different levels MGMT and the miRNAs considered here." (PMID 27057640, 2016). "αvβ3 integrin expression may predict benefit from integrin inhibition in patients with glioblastoma lacking MGMT promoter methylation." (PMID 26918452, 2016). "Survival data of 34 mostly chemotherapy-naïve glioblastoma patients treated with BCNU at 1st relapse were compared to 29 untreated control patients, employing a multiple Cox regression model which considered known prognostic factors including MGMT promoter hypermethylation." (PMID 26865253, 2016). "The TCGA Research Network reported that MGMT promoter methylation could serve as a predictive biomarker only in the glioblastoma classical subtype but not in the other subtypes (mesenchymal, proneural or neural)." (PMID 27158244, 2016). "In vitro, four glioblastoma-derived cell lines with and without methylguanine-DNA methyltransferase (MGMT) overexpression (U251, U87, U251-MGMT, U87-MGMT) were exposed to Vpr, temozolomide (TMZ), conventional photon irradiation (2 to 6 Gy) or to combinations thereof." (PMID 27275537, 2016).
glioblastoma (continued). "The weak association with improved outcome with cilengitide in patients with glioblastoma lacking MGMT promoter methylation in the phase II CORE trial may justify patient enrichment based on αvβ3 expression in tumor cells in future trials." (PMID 26918452, 2016). "In addition, MGMT hypermethylation (epigenetical silencing of the promoter and coding regions of the MGMT gene) is considered to be one of the principal mechanisms contributing to the TMZ sensitivity of glioblastomas." (PMID 25955568, 2015). "We showed that treatment with RO4929097 potentiated the TMZ effect on U87-R1 and the primary glioblastoma cell lines, including on MGG23 cells that were the only primary glioblastoma cells included to have an unmethylated MGMT promoter and high expression of MGMT." (PMID 24495907, 2014). "To evaluate whether APE1, NBN, PMS2, MGMT and PTEN mRNA also have a role in paediatric high grade gliomas we proceeded to investigate mRNA expression in 53 paediatric high grade gliomas and 27 paediatric glioblastomas." (PMID 25026297, 2014). "Second, the study suggests that MGMT promoter status might not have a treatment-independent prognostic value in older glioblastoma patients, because it did not have a significant impact on survival of those without TMZ chemotherapy." (PMID 24454798, 2014). "Finally, the TCGA dataset supports the prognostic value of the ZEB1/miR-200/c-MYB pathway for glioblastoma, as well as significant co-occurrence of ZEB1, MGMT and ROBO1 in these tumours, and decreased levels of EGFR phosphorylation with reduced ZEB1 expression." (PMID 23818228, 2013). "Additionally, we found that protein expression of ZEB1, but surprisingly not MGMT, correlated with reduced survival of glioblastoma patients, as well as with shorter duration of successful TMZ therapy." (PMID 23818228, 2013). "The detection of MGMT methylation does not provide useful information with regard to prognosis, but may predict whether patients with glioblastomas are able to benefit from temozolomide therapy." (PMID 23946790, 2013). "Interestingly, non-CIMP anaplastic gliomas showed a MGMT promoter methylation frequency similar to glioblastoma." (PMID 22810491, 2012). "However, previous studies considered promoter methylation of the MGMT gene not to be a reliable prognostic factor of responsiveness to alkylating agents in glioblastomas." (PMID 23245659, 2012). "This therapeutically disadvantageous protective effect is thought not to be present when MGMT is epigenetically silenced through promoter methylation as observed in many human cancers including glioblastoma, thus rendering cells more sensitive to alkylating drugs." (PMID 22428052, 2012). "Radiotherapy in combination with mTOR inhibition (temsirolimus) is an alternative schedule that has proved efficient in preclinical studies and is currently under evaluation in a clinical study of newly diagnosed glioblastomas in comparison to chemoirradiation and lack of MGMT methylation." (PMID 22530122, 2012). "The combination of cilengitide with sunitinib malate is tested in a pilot biomarker study and chemoradiotherapy with cilengitide or cetuximab are being investigated in a randomized, noncomparative trial in patients with newly diagnosed MGMT-promoter unmethylated glioblastoma (CeCil)." (PMID 22295207, 2011). "In spite of the improved MGMT activity depletion, there was no apparent survival benefit to dose-intense temozolomide when the same model was challenged with the two schedules, in this single treatment cycle model of glioblastoma." (PMID 20628383, 2010). "Of further direct translational relevance was the observation that KNS42 cells were found to have methylation in the MGMT promoter, but counter to the expectation in glioblastoma cells, this did not confer a sensitivity to in vitro treatment with the alkylating agent temozolomide." (PMID 19365568, 2009).